SLC35G3 (solute carrier family 35 member G3)
Description:
Testis-specific UDP-N-acetylglucosamine transporter that mediates transport of nucleotide sugars to facilitate the proper glycosylation of proteins critical for sperm function.
Synonyms: AMAC1; TMEM21A; FLJ40154
Tractability: Antibody: UniProt predicts a signal peptide or a membrane-spanning region.
Gene: Protein-coding gene on chromosome 17 (35,192,520 to 35,194,393, reverse strand). Ensembl gene ENSG00000164729.
Subcellular location: Golgi apparatus membrane
Gene Ontology:
Molecular function: UDP-N-acetylglucosamine transmembrane transporter activity
Biological process: glycoprotein biosynthetic process; UDP-N-acetylglucosamine transmembrane transport
Cellular component: Golgi membrane; membrane
Genetic constraint (gnomAD): Loss-of-function variants: 10 observed, 18.83 expected, observed/expected ratio (o/e) 0.53, 90% interval 0.33 to 0.9. The upper end of that interval is the gene's LOEUF score, 0.9, which puts it in group 3 of 6, group 1 being the genes least tolerant of losing a copy. Missense variants: 384 observed, 445.89 expected, observed/expected ratio (o/e) 0.86, 90% interval 0.79 to 0.94. Synonymous variants: 208 observed, 200.78 expected, observed/expected ratio (o/e) 1.04, 90% interval 0.92 to 1.16.
Homologues: Orthologues: macaque SLC35G6 (90% identical), dog SLC35G6 (87% identical), mouse Slc35g3 (82% identical), rat Slc35g3 (81% identical), Drosophila melanogaster CG5281 (14% identical). Paralogues in human: SLC35G6 (92% identical), SLC35G5 (92% identical), SLC35G4 (91% identical), SLC35G2 (28% identical), SLC35G1 (18% identical).
Diseases named in the same sentence as SLC35G3 in open-access papers:
SLC35G3 is named in the same sentence as 5 diseases in open-access papers, as found by Europe PMC text mining. Sharing a sentence is not in itself a finding about the gene and the disease. The quoted sentences say what the papers report.
Infertility (2 papers, 2025). "Reported human SLC35G3 mutations (F267L and T179HfsTer27) diminished the UDP-GlcNAc transporter activity of SLC35G3, implying infertility risks in males carrying these mutations." (PMID 40462929, 2025). "To further analyze the cause of infertility in Slc35g3 null male mice, we performed an in vitro fertilization (IVF) assay." (PMID 40462929, 2025).
male infertility (2 papers, 2025). The inability of the male to effect fertilization of an ovum after a specified period of unprotected intercourse. "In vitro studies further implicated latent male infertility due to SLC35G3 mutations." (PMID 40462929, 2025). "Furthermore, we demonstrated that human SLC35G3 also exhibits transporter activity, and proposed a loss-of-function mutation that may cause male infertility." (PMID 40462929, 2025). "Finally, we examined mutations in human SLC35G3 for their potential risk of male infertility." (PMID 40462929, 2025).
SLC35G3 also shares sentences with these, for which no sentence is quoted: colorectal cancer (1 paper); hepatocellular carcinoma (1); lung carcinoma (1).